MEG3 (maternally expressed 3)
Diseases named in the same sentence as MEG3 in open-access papers (continued):
Sharing a sentence is not in itself a finding about the gene and the disease.
triple-negative breast carcinoma (6 papers, 2015 to 2022). An invasive breast carcinoma which is negative for expression of estrogen receptor (ER), progesterone receptor (PR), and human epidermal growth factor receptor 2 (HER2). "Recently published studies have shown that Cisplatin induces scorch death through activating the MEG3/NLRP3/caspase-1/GSDMD pathway in triple-negative breast cancer." (PMID 35938142, 2022). "Moreover, the activation of MEG3 enhanced Cisplatin-induced pyroptosis in triple-negative breast cancer." (PMID 36685973, 2022). "So far the function of MEG3 in triple negative breast cancer is unknown and needs further investigation." (PMID 26537449, 2015). "Additionally, lncRNA maternally expressed gene 3 (MEG3) induced pyroptotic cell death in triple-negative breast cancer via MEG3/NLRP3/caspase-1/GSDMD signaling pathway in response to cisplatin treatment, which performed an anti-tumor effect both in vitro and in vivo." (PMID 35873495, 2022). "In triple-negative breast cancer, cisplatin activated MEG3/NLRP3/CASP-1 pathway to induce cell pyroptosis, which suggested that MEG3 was involved in the pyroptosis pathway of cisplatin therapy." (PMID 36281290, 2022).
anemia (5 papers, 2017 to 2025). A reduction in the number of red blood cells, the amount of hemoglobin, and/or the volume of packed red blood cells. "lncRNA MEG3 rs10132552 CC genotype carriers were related with increased risk of severe anemia when receiving radiochemotherapy." (PMID 35990252, 2022). "The most dramatic finding was that the MEG3 rs10132552 CC genotype had a greater than three-fold increased risk of developing grade 3–4 anaemia (OR = 3.001, 95%CI = 1.355–6.646, P = 0.007)." (PMID 28814798, 2017). "In addition, NPC patients with lncRNA MEG3 rs10132552 CC genotype were vulnerable to suffering chemoradiotherapy induced anemia." (PMID 34336850, 2021).
coronary artery disease (5 papers, 2018 to 2024). "Compared to individuals, the level of methylation of MEG3 decreased from 45.31 to 39.53 percent, which was associated with an increased risk of coronary heart disease." (PMID 36968595, 2023). "Lower Meg3 expression is found in patients with coronary artery disease (CAD), pulmonary arterial hypertension (PAH), and metabolic syndrome, but increased expression was found in diabetes type 2 and heart failure patients." (PMID 30893946, 2019). "Moreover, in the coronary artery disease (CAD) tissues, MEG3 level declines, and miR-21 expression has negative correlation with MEG3 expression." (PMID 30217221, 2018).
insulinoma (5 papers, 2017 to 2024). "In both human PNET samples and MIN6 murine insulinoma cells, the hypermethylation of the MEG3 promoter is associated with the downregulation of MEG3 compared to normal tissue." (PMID 38279330, 2024). "Indeed, Meg3 and c-MET levels are described to be inversely correlated, both in MEN1-associated PanNENs and sporadic insulinomas." (PMID 32537434, 2020). "DNA demethylating drugs reduce mouse insulinoma cell proliferation and restore MEG3 expression." (PMID 29069869, 2017).
Kagami-Ogata Syndrome (5 papers, 2015 to 2024). "Along the same lines, Kagami-Ogata syndrome (KOS) (OMIM #608149) is an imprinting disorder that in some cases is caused by gain of methylation in the MEG3 ICR." (PMID 39429790, 2024). "In Kagami-Ogata Syndrome (KOS14), conversely, the loss of MEG3 expression would correlate with increased DLK1 and RTL1 expression, now from both the parental chromosomes." (PMID 38613389, 2024). "These interesting findings in mice are relevant for our understanding of Kagami-Ogata Syndrome (KOS14), which is caused by the loss of expression of the MEG3 ncRNA polycistron and is characterised by dysmorphic growth and skeletal defects." (PMID 37686455, 2023).
myelodysplastic syndrome (5 papers, 2013 to 2018). A clonal hematopoietic disorder characterized by dysplasia and ineffective hematopoiesis in one or more of the hematopoietic cell lines. "Intriguingly, hypermethylation of the MEG3 promoter has been observed in approximately 50% of patients with myelodysplastic syndrome (MDS) and AML." (PMID 28407691, 2017).
Papillary Thyroid Cancer (5 papers, 2022 to 2025). "A study reported an analysis of publicly available single-cell RNA-sequencing data and found that MEG3 is primarily expressed by cancer-associated fibroblasts (CAFs) in papillary thyroid cancer (PTC) and that MEG3 is positively correlated with lymph node (LN) metastasis." (PMID 37373059, 2023).
Parkinson disease (5 papers, 2020 to 2023). A progressive degenerative disorder of the central nervous system characterized by loss of dopamine producing neurons in the substantia nigra and the presence of Lewy bodies in the substantia nigra and locus coeruleus. "MEG3 and ACVR1B were closely related to graft versus host disease, oxidative phosphorylation, Parkinson's disease, proteasome, ribosome, and splicesome." (PMID 37928394, 2023). "Furthermore, many of the predictions from MGI, KEGG and GO BP were related to the dysfunction of synapses and neurotransmitter transport, supporting the role of MEG3 in LTP and Parkinson’s disease." (PMID 36869839, 2023).
postmenopausal osteoporosis (5 papers, 2018 to 2024). Metabolic disorder associated with fractures of the femoral neck, vertebrae, and distal forearm. "On the other hand, lncRNA MEG3 attenuates the osteogenic differentiation of bone marrow mesenchymal stem cells from postmenopausal osteoporosis by targeting miR-30b-5p." (PMID 34455406, 2021). "For instance, a recent study demonstrated that lncRNA MEG3 suppressed the osteogenic differentiation of MSCs in postmenopausal osteoporosis." (PMID 31659145, 2019). "MEG3 has been demonstrated to upregulate miR-133a-3p and inhibit osteogenic differentiation in bone marrow MSCs from patients with postmenopausal osteoporosis, which also plays an essential role in osteogenic differentiation in bone marrow MSCs, partially by activating BMP4 transcription." (PMID 39628661, 2024). "However, another study of postmenopausal osteoporosis revealed that MEG3 inhibited the osteogenic differentiation of BMSCs." (PMID 29973283, 2018).
rheumatoid arthritis (5 papers, 2019 to 2024). A chronic, systemic autoimmune disorder characterized by inflammation in the synovial membranes and articular surfaces. "Besides, a study on rheumatoid arthritis described significantly low lncRNA MEG3 and this was augmented by its rising level during treatment." (PMID 38985298, 2024). "The later study reported the mechanistic impact of rs941576 in rheumatoid arthritis; the AA genotype carriers exhibited a significantly decreased serum MEG3 expression and BAX levels and increased hypoxia-inducible factor-1α and vascular endothelial growth factor levels." (PMID 38704452, 2024).
acute promyelocytic leukemia (4 papers, 2016 to 2022). An aggressive form of acute myeloid leukemia (AML), characterized by arrest of leukocyte differentiation at the promyelocyte stage, due to a specific chromosomal translocation t(15;17) in myeloid cells. "On one side, MEG3 was overexpressed in acute promyelocytic leukemia (APL), while exerting antitumor function in AML cell lines." (PMID 35615374, 2022). "The overexpression of Dlk1-Dio3 miRNAs in acute promyelocytic leukemia (APL) has been associated with the hypermethylation of conserved binding sites for the CCCTC-binding factor (CTCF, an enhancer blocking protein) at MEG3-DMR." (PMID 34062726, 2021).
alveolar rhabdomyosarcoma (4 papers, 2014 to 2024). A rapidly growing malignant mesenchymal neoplasm. "MEG3 CRNDE, LINC00340, and RMST (rhabdomyosarcoma 2 associated transcript) is also found in various cancers." (PMID 28321286, 2017). "The remaining four DElncRNAs (MEG3, maternally expressed gene 3; RMST, rhabdomyosarcoma 2-associated transcript; HNF1A-AS1, HNF1A antisense RNA 1; and PVT1, and plasmacytoma variant translocation 1) and two DEmiRNAs (hsa-mir-429 and hsa-mir-200a) appeared to be protective." (PMID 36101743, 2022). "Moreover, the presence of LOI at the delta-like non-canonical notch ligand 1 (DLK1) and MEG3 locus has been found to vary between two different histological subtypes of rhabdomyosarcoma (RMS)." (PMID 38812777, 2024).
ankylosing spondylitis (4 papers, 2021 to 2024). An autoimmune chronic inflammatory disorder characterized by inflammation in the vertebral joints of the spine and sacroiliac joints. "Another study showed significantly downregulated lncRNA MEG3 in the serum of patients diagnosed with ankylosing spondylitis (AS)." (PMID 38985298, 2024). "Not much is known regarding the other lncRNAs in UC settings, but recently Meg3 was shown to inhibit the inflammatory response in ankylosing spondylitis characterized by chronic inflammation." (PMID 36685283, 2022). "In addition, MEG3 inhibits the inflammatory response of ankylosing spondylitis, and MEG3 inhibits HMEC-1 cell growth and migration." (PMID 33425489, 2021).
autoimmune disease (4 papers, 2013 to 2025). A disorder resulting from loss of function or tissue destruction of an organ or multiple organs, arising from humoral or cellular immune responses of the individual to their own tissue constituents. "All but four out of 26 red group signals (PRF1, CTRB2, MEG3 and RNLS) were associated with other autoimmune diseases found in the Open Targets Genetics portal." (PMID 39749473, 2025). "Furthermore, Multiple sclerosis, which is an autoimmune disease characterized by chronic inflammation of the central nervous system, revealed low expression levels of lncRNA MEG3 in relapsing phase patients in comparison to patients in remission and control groups." (PMID 38985298, 2024).
brain cancer (4 papers, 2011 to 2025). A primary or metastatic malignant neoplasm affecting the brain. "Some of the most representative lncRNAs, such as HOTAIR, MALAT1, and MEG3, have been consistently validated over the years, where their role in malignant brain tumors appears evident." (PMID 41149459, 2025).
brain tumor (4 papers, 2013 to 2023). "The relation between expression levels of MEG3 and immune responses has been confirmed in a study in brain tumors." (PMID 37907501, 2023). "For example, MEG3 is recognized as a novel tumor suppressor for brain tumor." (PMID 27642276, 2016). "Next, Ki‐67 immunohistochemistry was implemented on the brain tumor tissues in the nude mice, which addressed that the number of Ki‐67 positive cells was reduced in mice upon MTE treatment, while the number of which was increased in mice treated with both MTE and sh‐MEG3." (PMID 36756719, 2023).
cardiomyopathies (4 papers, 2016 to 2023). "Mounting evidence has associated MEG3 with a large range of cardiomyopathies, and it is worth exploring their molecular mechanisms." (PMID 36968595, 2023). "Lnc‐MEG3 expression was positively correlated with cardiomyopathy, APACHE II score, SOFA score, Scr, TNF‐α, IL‐1β, IL‐6, and IL‐17, 28‐day deaths, while negatively correlated with albumin." (PMID 34956235, 2021).
cholangiocarcinoma (4 papers, 2019 to 2022). A carcinoma that arises from the intrahepatic biliary tree (intrahepatic cholangiocarcinoma) or from the junction, or adjacent to the junction, of the right and left hepatic ducts (hilar cholangiocarcinoma). "MEG3 also can inhibit cholangiocarcinoma proliferation and invasion by inhibiting the major components of the PRC1 complex, B lymphoma Mo-MLV insertion region 1 (Bmi1), and RING finger protein 2 (RNF2)." (PMID 36551518, 2022). "In cholangiocarcinoma, MEG3 level was found to have been significantly decreased in cholangiocarcinoma tissues and cells as compared to that in nontumor controls and it suppressed cell proliferation and invasion via regulating Bmi1/RNF20." (PMID 31729423, 2019).
epilepsy (4 papers, 2022 to 2025). A brain disorder characterized by episodes of abnormally increased neuronal discharge resulting in transient episodes of sensory or motor neurological dysfunction, or psychic dysfunction. "Surprisingly, Meg3 dysregulation has been identified in temporal lobe epilepsy through recent RNA sequencing data and Meg3 overexpression in the hippocampus ameliorates the progression of epilepsy." (PMID 36942475, 2023).
gestational diabetes (4 papers, 2022 to 2024). Carbohydrate intolerance first diagnosed during pregnancy. "MEG3 overexpression, meanwhile, was able to prevent human villous trophoblast HTR-8/SVneo from proliferating, migrating, and invading while inducing apoptosis, indicating that MEG3 may be implicated in the development of gestational diabetes mellitus and playing a significant role." (PMID 37745705, 2023). "Human umbilical vein endothelial cells (HUVEC) from gestational diabetes mellitus have elevated MEG3 expression, which affects fetal endothelial function through the PI3K signaling pathway." (PMID 37745705, 2023). "A previous study also found that the expression of miR-345-3p in blood and placental villi of pregnant women with gestational diabetes mellitus is downregulated, which seems to be a downstream target of lncRNA MEG3." (PMID 34845670, 2022). "MEG3 was found to be highly expressed in the blood and placental villus tissues of gestational diabetes mellitus (GDM)." (PMID 36523500, 2022).
Hirschsprung disease (4 papers, 2017 to 2024). Hirschsprung disease (HSCR) is a congenital intestinal motility disorder that is characterized by signs of intestinal obstruction due to the presence of an aganglionic segment of variable extent in the terminal part of the colon. "Downregulation of lncRNA MEG3 inhibited cell migration and proliferation in patients with Hirschsprung's disease." (PMID 39346787, 2024).
Impaired glucose tolerance (4 papers, 2013 to 2024). An abnormal resistance to glucose, i.e., a reduction in the ability to maintain glucose levels in the blood stream within normal limits following oral or intravenous administration of glucose. "It has also been reported that the silencing of the lncRNA MEG3 resulted in impaired glucose tolerance, decreased insulin secretion, and fewer insulin-positive cells, indicating that MEG3 may be a novel β cells regulator." (PMID 37108143, 2023). "The db/db mice islets showed significantly decreased expression of lncRNA Meg3, and the islet-specific knockdown of lncRNA Meg3 resulted in less insulin synthesis and secretion but larger scale of β cell apoptosis, consequently lead to impaired glucose tolerance." (PMID 32095365, 2020).
infarction (4 papers, 2018 to 2020). A localised pathological necrosis of tissue resulting from obstruction of the blood supply usually by a thrombus, an embolus, or vascular torsion. "Several lncRNAs with a GC-AG intron were described to play a role in neuron development and growth like the MEG3 gene, the NEAT1 gene, the SOX2-OT gene, the GDNF-AS1 (GDNF antisense RNA 1) gene and the MIAT (myocardial infarction associated transcript)." (PMID 32499820, 2020). "Furthermore, MEG3 functions as a competing endogenous RNA for miR-181b to regulate 12/15-LOX expression in middle cerebral artery occlusion-induced ischemic infarct of brain nerve cells." (PMID 30579356, 2018). "In addition, lncRNA MEG3 knockdown by lentivirus‐mediated delivery could reduce infarct size and cardiac fibrosis and improve cardiac function post‐infarction." (PMID 31631486, 2019).
metastatic tumor (4 papers, 2016 to 2025). "We also examined TCGA PTC transcriptomes and found that MEG3 is expressed higher in metastatic tumors compared to normal, though the former is poorly represented in this study (n = 8)." (PMID 36231143, 2022).
Myocardial fibrosis (4 papers, 2021 to 2023). "Other studies have shown that MEG3 participates in the development of myocardial fibrosis and prevents myocardial remodeling by regulating the production of MMP-2 by CFs in vitro and in vivo." (PMID 33407475, 2021). "The lncRNA Meg3 is expected to be a new target for the treatment of cardiac remodeling and myocardial fibrosis." (PMID 34235188, 2021). "So, it is essential to investigate whether MEG3-adjacent gene expression contributed to its regulation of endothelial cells and myocardial fibrosis." (PMID 36968595, 2023).
periodontitis (4 papers, 2019 to 2024). An acute or chronic inflammatory process that affects the tissues that surround and support the teeth. "Periodontitis was associated with the downregulation of both lncRNA MEG3 and lncRNA MAFG-AS1." (PMID 38985298, 2024). "Altogether, the findings presented in this study highlights that lncRNA MEG3 was determined as a biomarker as periodontitis inhibitor because of the new-found mechanism underlying lncRNA MEG3/miR-27a-3p/IGF1 axis via PI3K/Akt signaling pathway by promoting osteogenic differentiation in PDLSCs." (PMID 31398715, 2019). "Opposite to the qRT-PCR results of lncRNA MEG3 expression, miR-27a-3p expression in PDLSCs was up-regulated in periodontitis periodontal tissues compared with healthy periodontal tissues, and down-regulated after 14 days of osteogenic induction." (PMID 31398715, 2019). "Comparison between periodontitis tissues and heathy samples indicated that expression of lncRNA MEG3 was significantly down-regulated in pPDLSCs compared with in hPDLSCs." (PMID 31398715, 2019). "To conclude, lncRNA MEG3 sponged miR-27a-3p to up-regulate IGF1 to activate PI3k/Akt signaling pathway to promote PDLSC osteogenic differentiation in periodontitis." (PMID 31398715, 2019). "For instance, in a study on periodontitis, lncRNA MEG3 was downregulated." (PMID 38985298, 2024). "Furthermore, knockdown of lncRNA MEG3 inhibited the osteogenic differentiation of periodontal ligament stem cells (PDLSCs) in periodontitis." (PMID 35611986, 2022). "Depletion of lncRNA MEG3 inhibits osteogenesis of PDLCs in periodontitis." (PMID 34868829, 2021). "Moreover, our result showed that lncRNA MEG3/miR-27a-3p/IGF1 axis definitely played a significant role in understanding the pathogenesis of periodontitis for better prognosis." (PMID 31398715, 2019). "However, because of the limitation of the samples we researched in this study, further confirmation should be needed in prospective researches of the pathological and physiological mechanism according to lncRNA MEG3/miR-27a-3p/IGF1 axis in periodontitis PDLSCs." (PMID 31398715, 2019). "Similar to the expression of lncRNA MEG3, IGF1 expression was lower in periodontitis periodontal tissues, compared with healthy periodontal tissues." (PMID 31398715, 2019).